CD80 (CD80 molecule)
Diseases named in the same sentence as CD80 in open-access papers (continued):
Sharing a sentence is not in itself a finding about the gene and the disease.
cancer (continued). "Another known mechanism of immune evasion by cancer cells is to increase their expression of checkpoint ligands, such as PD-L1, CD80, and CD86 and promote T cell tolerance." (PMID 30740111, 2018). "PD-L1, which is expressed on many cancer and immune cells, plays an important part in blocking the “cancer immunity cycle” by binding programmed death-1 (PD-1) and B7.1 (CD80), both of which are negative regulators of T-lymphocyte activation." (PMID 28405244, 2017). "It is known that CD80 is the most important costimulatory molecules on the surface of DCs to provide the crucial second signal for the proper stimulation of cancer antigen-specific naive T cells." (PMID 28337449, 2017). "We clarified the alterations of mRNA of major immune regulators PD-L1, FOXP3, CD80, CD40, and CD14 in PBMCs of cancer patients and the association of these alternations with disease progression." (PMID 26942414, 2017). "Further investigation is required in vivo and in translational research of CD80 function in the cancer microenvironment." (PMID 26942414, 2017). "Consistent with a pivotal role for CD80 in cancer immune surveillance, neutralization of CD80 caused a significant increase in HGD, whereas enhancing CD80 signaling with anti-CTLA4 protected mice from colon carcinogenesis progression." (PMID 25595911, 2015). "In our series, CD80 mRNA peaked in mucosal samples from patients with UC and dysplasia and resulted down regulated in patients with UC and cancer." (PMID 25595911, 2015). "DAC treatment leads to demethylation of the promoter region of CD80 gene in cancer cells, leading to the expression of CD80, which stimulates T cell responses." (PMID 23671644, 2013). "The up-regulated genes include those encoding for cancer testis antigens such as P1A and MAGE-A1 and many cell surface molecules such as CD80." (PMID 23671644, 2013). "To further characterize DCs in cancer patients, we next determined their expressions of the surface markers HLA-DR, CD80, and CD86 by flow cytometry." (PMID 20565840, 2010). "Our data confirm that in cancer patients, DCs display an 'immature' phenotype with lower levels of accessory signals for T cell activation such as CD80 and CD86 than those expressed on DCs from normal healthy controls." (PMID 20565840, 2010). "In conclusion, our study has elucidated the expression profile of CD80 in FLT3-ITD AML cells and proposed a hitherto unrecognized hypothesis that ROS drives CD80 expression as a regulator of the cancer cell adaptive response." (PMID 40746567, 2025). "Interestingly, a simultaneous increase in PD-1 and CD80 on the surface of T cell-derived exosomes was revealed in cancer patients." (PMID 41294803, 2025). "Our findings suggest that m6A readers might selectively regulate immune checkpoint expression, affecting CD70/CD80 dynamics in various cancer types." (PMID 40565233, 2025). "Additionally, similar to the overexpression of the co-stimulatory molecule CD80 in cancer cells, a soluble form of CD80 has also been demonstrated to potentiate antitumor immunity." (PMID 40746567, 2025). "Our analysis of HCC using the TCGA database confirmed the correlation of TKT with additional ICP genes, including CD44, CD80, CD86, and CTLA-4, which may explain the association of TKT overexpression with poorer prognoses in patients with cancer." (PMID 40230848, 2025). "The authors propose that combining antibodies targeting PD-L1 (to disrupt both trans PD-1/PD-L1 and cis PD-L1/CD80 interactions) with anti-CTLA-4 antibodies might further enhance T-cell reinvigoration in cancer patients." (PMID 41425548, 2025). "In the HNSCC cohort, the presence of <71% Ecad+ cancer cells, >21% Vim+, CD80+ and CD155+ cancer cells, and >7% Ecad−Vim+, Ecad−CD80+ and Ecad−CD155+ cancer cells might be risk factors for anti-PD-1/PD-L1 resistance." (PMID 38914547, 2024).
cancer (continued). "Interestingly, our findings demonstrate that most epithelial cancer cells express PD-L1, whereas hybrid E/M and mesenchymal cancer cells reduce PD-L1 expression and upregulate CD80 and CD155 expression, which are the ligands of CTLA-4 and TIGIT receptors." (PMID 38914547, 2024). "In cancer, CTLA4 is harnessed by cancer cells to hinder the antitumor immune response through manipulation of the expression of CTLA4 ligands (CD80 and CD86) on APCs within the tumor microenvironment, enabling CTLA4 on regulatory T cells (Tregs) to suppress cytotoxic T cell activity." (PMID 39409893, 2024). "In addition, other studies have indicated an association of rs231775 with CTLA-4 expression and an effect on the affinity of CTLA-4 for B7-1 (CD80) in many cancers." (PMID 38723011, 2024). "However, the response to ICI treatment in older cancer patients expressing CD80 remains dichotomous and requires additional research to elucidate." (PMID 38590525, 2024). "Thus, cancer cell fragments generated by carbon ion irradiation induce cancer-specific CD8+ T cells through the cross-presentation of CD80 and CD86 on DCs." (PMID 38474078, 2024). "In addition, further studies are warranted to check the impact of CD80 blockade on TISC-targeted anti-cancer therapy." (PMID 38891044, 2024). "PDT with PS redaporphin stimulates CD80 overexpression on cancer cells." (PMID 39057071, 2024). "Soluble CD80 as a therapeutic agent, combined with αPD-1 monoclonal antibody therapy, may be more effective for cancer patients than αPD-1 monotherapy." (PMID 36892747, 2023). "Given the role of CD80 in regulating the immune system is complicated, providing the opportunity for CD80 interactions to be involved in various diseases including multiple autoimmune diseases, and various cancers." (PMID 35814211, 2022). "Our results also revealed that the involvement of an adaptive response of the antitumor effect of H89 may be related to its ability to reduce the expression of PD-L1 and CD80 on cancer cells." (PMID 35572581, 2022). "Programmed cell death 1 (PD1): programmed cell death 1 ligand 1 (PDL1), and cytotoxic T lymphocyte-associated protein 4 (CTLA4): B-lymphocyte activation antigen B7 (B7-1; also termed CD80) are the most extensively studied immune checkpoints for cancer immunotherapy." (PMID 35493449, 2022). "CD80 can be expressed in immune cells as well as some cancer cells." (PMID 35211415, 2022). "We depicted the expression pattern of CD80 among multiple cancer sites." (PMID 35814211, 2022). "However, the interaction of CTLA-4 on naive T cells with CD80 on cancer cells produces an inhibitory signal for T cell activation, leading to the inhibition of T cell activation and suppression of the immune response." (PMID 36142412, 2022). "Furthermore, CSCs exert immunosuppressive functions including the expression of the immune checkpoints such as CD274 (best known as PD-L1) and CD80 (also known as B7.1) by preventing T cell activity and cancer dormancy." (PMID 34572009, 2021). "Anti‐TGF‐β antibodies rendered TGF‐β‐responsive cancer stem cells sensitive to adoptive T‐cell transfer treatment, of which the efficacy could be hindered by CD80/CTLA4‐mediated immunosuppression." (PMID 33932112, 2021). "As for co-stimulators, GMFG was highly associated with CD80 and CD28 in most cancers." (PMID 33863293, 2021). "Interestingly, the Oligo-Fucoidan-treated cancer cells also upregulated F4/80 and CD80 mRNA levels and these effects were additively enhanced by DPI cotreatment." (PMID 32059469, 2020). "Given that hematological malignancies represent a broad group of cancers we also determined whether co-expression of high CD80 and high PTK2 was restricted to particular hematological malignancies by subdividing this category based on origin." (PMID 31959281, 2020).
cancer (continued). "PD-L1 (also called B7-H1 or CD274), which is expressed on many cancer and immune cells, plays an important part in blocking the ‘cancer immunity cycle’ by binding programmed death-1 (PD-1) and B7.1 (CD80), both of which are negative regulators of T-lymphocyte activation." (PMID 29163797, 2017). "This association has been found to be notable at the dysplastic stage of carcinogenesis when the CD80-driven immune surveillance process might be critical in preventing cancer cells from escaping." (PMID 27377375, 2016). "In addition, we also found that a transient, low-dose DAC treatment can induce CD80 gene expression in a variety of human cancer cells." (PMID 23671644, 2013). "In addition, we also showed that a transient, low-dose DAC treatment can induce CD80 gene expression in a variety of human cancer cells." (PMID 23671644, 2013). "Interestingly, with nanoparticle flow cytometry, we found that more than half of circulating PD-1+ or CD80+ sEVs cocarried both PD-1 and CD80, revealing a synchronised increase in sEV PD-1 and CD80 (hereafter PD-1/CD80) levels in the circulation of cancer patients." (PMID 38719909, 2024). "However, CD80 has also been reported to be overexpressed in a number of cancers including BC." (PMID 36387279, 2022). "In recent years, immune checkpoint blockade (ICB) therapy has caused a paradigm shift in cancer immunotherapy; it primarily inhibits various checkpoints that control host T cell activity by regulating the immune checkpoint interactions, PD-1/PD-L1 and CTLA-4/CD80." (PMID 36142412, 2022). "Therefore, in this study, we attempted to convert the negative CTLA4-CD86/CD86 signal by generating a novel CTLA4 signaling pathway in T cells to disrupt the interaction of immune checkpoint inhibitors CTLA4 and CD80/CD86 to effectively treat CD80/CD86-expressing cancer." (PMID 33868277, 2021). "We identified a cancer stem-like cell (CSC) population enriched in patients with partial response (PR) to neoadjuvant chemoimmunotherapy, characterized by high CD80 expression." (PMID 41677629, 2026). "When comparing PeCa patients and cancer-free controls, four inhibitory sICs (IDO, TIM-3, CD80, and CTLA-4) were found at significantly higher levels in the PeCa group." (PMID 41705256, 2026). "recently reported that PD-1/PD-L1 cancer immunotherapy also necessitates CD28 co-stimulation for CD8 T cell rescue, highlighting the crucial role of the CD80/CD28 pathway." (PMID 40746567, 2025). "This is supported by recent studies, which have shown that blockade of CD80 and CD86 following immunotherapy can improve outcomes in preclinical cancer models." (PMID 41417245, 2025). "Antigen-presenting molecules like MHC-I, MHC-II, co-inhibitory molecules (CTLA4), or co-stimulatory molecules (CD80, CD86) are crucial for presenting cancer antigens to T cells and triggering an immune reaction." (PMID 39980072, 2025). "Increasing evidence supports its function as a modulator of key immune regulatory molecules, including CD70, CD80, and TIGIT, influencing cancer immune evasion." (PMID 40565233, 2025). "We noticed a widespread dysregulation of RNA modification enzymes across multiple cancer types, focusing on the regulation of the immune checkpoints CD70, CD80, and TIGIT." (PMID 40565233, 2025). "Our findings support a model in which RNA modifications, particularly m6A, act as fine-tuners of CD70, CD80, and TIGIT expression across multiple cancer types." (PMID 40565233, 2025). "In the presence of immune checkpoint inhibitors targeting the CTLA-4/CD80 and PD-1/PDL-1 signaling pathways, these pathways are inhibited, and T cells are reactivated, leading to the death of cancer cells." (PMID 41357573, 2025). "CTLA-4, a transmembrane protein expressed on T lymphocytes, competitively binds to ligands CD80 (B7.1) and CD86 (B7.2) on antigen-presenting cells (APCs), and prevents T-cells from killing other cells, including cancer cells." (PMID 40563393, 2025).
cancer (continued). "Looking at the cancer cells, we observed a reduction in the number of LDHC-silenced cancer cells expressing PD-L1, PD-L2 and CD80, and decrease in the cell surface expression of PD-L2, Gal-9, PVR, HLA-DR and VISTA." (PMID 40108668, 2025). "Epithelial cancer cells, through the PD-1/PD-L1 pathway, and mesenchymal cancer cells, through the CTLA-4/CD80 and TIGIT/CD155 pathways, differentially block antitumor immune responses and determine the response to ICB therapies." (PMID 38914547, 2024). "Coexpression of CD80 and PD-L1 on cDCs positively correlated with enhanced CTL priming capacity against cancer, in agreement with increased formation of a CD28-costimulatory CD80:PD-L1 heterodimer." (PMID 38349740, 2024). "The frequency of CD80+Ecad+ and CD155+Ecad+ cancer cells specifically increased in mixed patient cSCCs, suggesting that the upregulation of these IC ligands is associated with the enrichment of hybrid E/M cancer cells at intermediate cSCC stages." (PMID 38914547, 2024). "In contrast, EpCAMlow, EpCAM− and full mesenchymal cancer cells downregulated the expression of PD-L1, CD112, and Gal9, and upregulated the expression of CD80 and CD155, ligands of CTLA-4 and TIGIT, respectively." (PMID 38914547, 2024). "As predicted, the administration of P21 to only DCs or cancer cells slightly enhanced DC maturation (CD11C+CD40+, CD80+, or CD86+) compared with the untreated group." (PMID 38994018, 2024). "The frequency of CD80+ and CD155+ cancer cells increased in mixed and even more so in mesenchymal patient cSCCs, being in the latter tumors where CD80 and CD155 expression was mainly observed in cancer cells that lost E-cadherin expression." (PMID 38914547, 2024). "The obtained results demonstrated significantly elevated levels of CD80, CD86, CD279 and CD274 expressing leukocyte populations in the cancer patient group, while the numbers of NK cells and CD8- and CD25-positive cells were decreased." (PMID 39456247, 2024). "Oncogenic signaling can also lead to the upregulation of immune-escape proteins in cancers, such as CD274, CD80 and CD86." (PMID 38840185, 2024). "Immune checkpoint therapy has shown considerable promise in treatment of cancers currently, many immune checkpoints are highly positively correlated with BAX, such as ENTPD1, CD80, and CD28." (PMID 39074253, 2024). "Exposure to cancer cells for 48 hours in vehicle conditions maintained THP1-derived macrophages with traditional marker expression, with 30% M0 cells expressing CD80 and 10% expressing CD206, 60% M1 cells expressing CD80, and 26% M2 cells expressing CD206." (PMID 39287565, 2024). "Several inhibitory immunoreceptors, including but not limited to CD28, CD80, CD86, CTLA4, CD276, and CD274, have been identified and studied in cancer in recent decades." (PMID 38831187, 2024). "Conversely, knockdown of S100A11 in HCC cells increased the expression of anti-cancer M1 macrophage markers CD80 and CD86 but suppressed the expression of pro-cancer M2 markers CD204 and CD206 upon co-culture with THP-1 derived macrophages." (PMID 38169544, 2024). "In step 3 of the cancer-immunity cycle, antigen recognition through T cell receptors and the interaction of CD28 on T cells with CD80/CD86 on DCs are necessary for full T cell activation." (PMID 36980950, 2023). "The CD80 (B7-1) and CD86 (B7-2) checkpoint proteins expressed by immune and cancer cells bind to CTLA-4 on T-cells and repress TCR/HLA-class-I-mediated activation." (PMID 37232754, 2023). "The levels of cytokines such as IL1a, IFNB1, CD80, CD86, and CXCL10, which are important for inducing an immune response by macrophages within cancer tissue, were upregulated in PBMCs in a RIG-I-dependent manner." (PMID 37543704, 2023). "Our analysis revealed a positive association between the expression of P2RY6 and immunosuppressive genes such as CD86, CD80, IL2RA, TGFB1, and LGALS9 in pan-cancer." (PMID 37880703, 2023).
cancer (continued). "The proportion of CD80+ cells and CD86+ cells in CD11b−F4/80+ cells were significantly lower in cancer-bearing mice than in non-cancer-bearing mice." (PMID 37553633, 2023). "CD80 and CD86 are ligands for CTLA4 and are expressed as markers of M2-type macrophages in various cancers." (PMID 37838657, 2023). "The ARMG risk score showed significantly positive relation with immunoinhibitors TGFB1 and VTCN1, and was negatively related with immunostimulators CD27, CD28, CD40LG, CD80, ENTPD1 and ICOS in pan-cancer." (PMID 38090588, 2023). "In vitro, PDT with the particles induced cancer cell death, and incubation of PDT-treated cancer cells with BMDC induced upregulation of maturation markers CD80 and CD86." (PMID 36839652, 2023). "Cancer cells treated with Amy-F showed a considerable reduction in the CD4, CD80 expression, whereas, induced elevation in CD8 and NKG2D expression was observed in Amy-F treated BCCs when compared to the RT group." (PMID 37210478, 2023). "In various types of cancer, findings between NNMT and immunostimulator gene expression showed a high connection (p < 0.05), including TNFSF13B, TNFRSF8, TNFSF14, IL6, IL2RA, CD80, CD27, and CD86." (PMID 36386816, 2022). "Decreased expression of MHC, CD80 and CD86 on APCs correlates with impaired T cell responses and immunosuppression in cancer." (PMID 35660630, 2022). "Second, most immuno-stimulators, such as MICB, MICA, CD80, ICOS, CD27, and various TNFSFs (all P < 0.05), were expressed at higher levels in PTPRD/PTPRT mutant cancers, compared with the WT." (PMID 36248841, 2022). "It should also be noted that PTX3 positively correlated with CD80, an essential costimulatory molecule in activating T cells, which further proved the dual roles of PTX3 in cancer immunity." (PMID 35855654, 2022). "Comparison of the CD80 and PD-1 binding sites on PD-L1 enabled the identification of a potential antibody binding region able to confer specificity for the inhibition of PD-1 binding only, which may offer therapeutic benefits to counteract cancer cell evasion of the immune system." (PMID 36470427, 2022). "As previously reported, in the cancer-immunity cycle, CD28: (CD80, CD86), CD40, CD27, HVEM, GITR: GITRL, ICOS, and TLR-2 are stimulatory factors, while TIM-3, PD-L1: PD-1, PD-L1: (CD80, CD86), CTLA-4: (CD80, CD86), BTLA, and LAG-3 are inhibitory factors." (PMID 35419462, 2022). "Regarding gene expression, cancer immune evasion-related genes were found up-regulated in the negative BL samples, such as CD274 (alias PD-L1), IDO1, LAG-3, CTLA4, and CD80 and CD86 genes, required for the activation of the inhibitory activity of CTLA4." (PMID 34680332, 2021). "The expression levels of CD80 and CD86 in U937 cells co-cultured with rapamycin-pretreated cancer cells were increased compared to those of the control group, whereas, CD163 expression was decreased, in both HeLa and SiHa cell co-cultures." (PMID 33390854, 2021). "The B. sennaarensisare toxins regulate the expression of MHC-II, CD80, and CD-86, as well as interferon- γ (IFN-γ) and interleukin-17 (IL-17), mediators that are involved in various chronic pathologies and cancer as demonstrated after in vivo tests." (PMID 34795699, 2021). "To further investigate the effects of lipotecan on cancer immunogenicity, we analyzed the levels of MHC class I and CD80 by flow cytometry." (PMID 33799527, 2021). "Antibody-based blockade of CTLA4 binding to CD80/CD86 is reported to promote CD80/CD86 interactions with the immune co-stimulatory signal, CD28, and re-activation of T cell activity to kill cancer cells." (PMID 33406733, 2021). "The results showed that the five TLR4 prognosis-related cancers KIRC, SKCM, STAD, TGCT, and UCEC were related to ICOS, CTLA4, CD28, and CD80." (PMID 34631699, 2021).